GLRB (glycine receptor beta)
Description:
Subunit of heteromeric glycine-gated chloride channels. Plays an important role in the down-regulation of neuronal excitability. Contributes to the generation of inhibitory postsynaptic currents.
Synonyms: HKPX2
Tractability: Small molecule: an approved drug acts on it; a structure with a bound ligand is known; a high-quality ligand is known; it belongs to a druggable protein family. Antibody: UniProt places it where antibodies can reach, with high confidence; its Gene Ontology location is reachable by antibodies, with high confidence; UniProt predicts a signal peptide or a membrane-spanning region. PROTAC: ubiquitination databases record sites on it; a small molecule that binds it is known.
Gene: Protein-coding gene on chromosome 4 (157,076,100 to 157,172,090, forward strand). Ensembl gene ENSG00000109738.
Subcellular location: Postsynaptic cell membrane; Synapse; Cell projection, dendrite; Cell membrane; Cytoplasm
Pathways (Reactome):
Neuronal System: Neurotransmitter receptors and postsynaptic signal transmission
Gene Ontology:
Molecular function: extracellularly glycine-gated chloride channel activity; extracellularly glycine-gated ion channel activity; glycine binding; protein binding; excitatory extracellular ligand-gated monoatomic ion channel activity; extracellular ligand-gated monoatomic ion channel activity; monoatomic ion channel activity; protein-containing complex binding; transmembrane signaling receptor activity; transmitter-gated monoatomic ion channel activity involved in regulation of postsynaptic membrane potential
Biological process: chemical synaptic transmission; chloride transmembrane transport; monoatomic ion transport; nervous system development; neuropeptide signaling pathway; startle response; synaptic transmission, glycinergic; chloride transport; excitatory postsynaptic potential; monoatomic ion transmembrane transport; regulation of postsynaptic membrane potential
Cellular component: cytoplasm; glycine-gated chloride channel complex; plasma membrane; glycinergic synapse; postsynaptic membrane; synapse; dendrite; GABA-ergic synapse; membrane; postsynaptic specialization
Genetic constraint (gnomAD): Loss-of-function variants: 6 observed, 15.88 expected, observed/expected ratio (o/e) 0.38, 90% interval 0.21 to 0.75. The upper end of that interval is the gene's LOEUF score, 0.75, which puts it in group 3 of 6, group 1 being the genes least tolerant of losing a copy. Missense variants: 202 observed, 225.66 expected, observed/expected ratio (o/e) 0.9, 90% interval 0.8 to 1.01. Synonymous variants: 82 observed, 87.29 expected, observed/expected ratio (o/e) 0.94, 90% interval 0.79 to 1.13.
Homologues: Orthologues: chimpanzee GLRB (99% identical), macaque GLRB (99% identical), dog GLRB (99% identical), pig GLRB (99% identical), rabbit GLRB (98% identical), guinea pig GLRB (97% identical), rat Glrb (97% identical), mouse Glrb (97% identical), tropical clawed frog glrb (92% identical), zebrafish glrbb (84% identical), zebrafish glrba (79% identical). Paralogues in human: GLRA3 (44% identical), GLRA2 (43% identical), GLRA1 (43% identical), GABRB1 (31% identical), GABRB2 (31% identical), GABRB3 (31% identical), GABRQ (29% identical), GABRR2 (28% identical), GABRR1 (28% identical), GABRR3 (28% identical), GABRA4 (27% identical), GABRG3 (27% identical), and 33 more.
Diseases named in the same sentence as GLRB in open-access papers:
GLRB is named in the same sentence as 11 diseases in open-access papers, as found by Europe PMC text mining. Sharing a sentence is not in itself a finding about the gene and the disease. The quoted sentences say what the papers report.
hyperekplexia (6 papers, 2014 to 2025). "Interestingly, a male patient possessing both missense and splice site mutations in GLRB, a β-subunit of the pentameric GLRs, has been reported to display hyperekplexia." (PMID 27506666, 2016). "Hyperekplexia results from mutations in GLRA1 and GLRB encoding the human glycine receptor and also the glycine transporter SLCA5." (PMID 26968164, 2016). "Patients diagnosed with startle disease/hyperekplexia do not always carry mutations in the known associated disease genes (GLRA1, GLRB, SLC6A5)." (PMID 37903619, 2023).
startle disease (5 papers, 2011 to 2025). "Hereditary hyperekplexia (HKPX) is a rare neurogenetic disorder caused by mutations in glycine signaling genes, such as GLRB." (PMID 40337415, 2025). "Within our patient cohort several patients diagnosed for startle disease do not carry a mutation in the known common genes, i.e., GLRA1, GLRB, SLC6A5." (PMID 37903619, 2023).
Anxiety (3 papers, 2017 to 2020). Intense feelings of nervousness, tension, or panic often arise in response to interpersonal stresses. "Recently, a genome-wide association of GLRB with categorical (panic disorder (PD)) and dimensional (agoraphobia (AG)) forms of fear and anxiety has been reported, in particular for rs7688285 which was associated with GLRB expression changes in post mortem tissue and reporter gene assays." (PMID 28872638, 2017). "We thus provide further support for the role of GLRB, which is listed under the arousal gene list in the RDoC matrix, for a neurofunctional intermediate phenotype associated with enhanced defensive system reactivity that may increase the vulnerability to develop pathological forms of anxiety." (PMID 28872638, 2017). "While human GLRB risk allele carriers show anxiety symptoms, they do not suffer from pathological anxiety." (PMID 32848605, 2020). "Using TargetScan 6.2 and Diana microT-CDS, in silico prediction yielded high scores for 3’UTR binding of hsa-miR-579-3p for GLRB, HTR2B, and NPY5R, in line with regulation of possible anxiety candidate genes." (PMID 30341278, 2018).
panic disorder (3 papers, 2017 to 2020). An anxiety disorder characterized by multiple unexpected panic attacks with persistent concern of recurring attacks. "A recent genome-wide association study (GWAS) identified four genetic variants rs78726293, rs191260602, rs17035816 and rs7688285 in GLRB gene to be associated with panic disorder (PD) risk." (PMID 29042589, 2017). "Previous studies linked the GLRB gene to anxiety disorders, like panic disorder and agoraphobia." (PMID 32848605, 2020).
agoraphobia (2 papers, 2017 to 2020). An anxiety disorder characterized by an intense, irrational fear of venturing out into open places or situations in which help (or escape) might not be available should excessive anxiety or panic symptoms develop. "A GWAS study recently demonstrated single nucleotide polymorphisms (SNPs) in the human GLRB gene of individuals with a prevalence for agoraphobia." (PMID 32848605, 2020). "A recent GWAS study used an Agoraphobic Cognition Questionnaire (ACQ) and identified several allelic variations within the human GLRB gene (intronic region and flanking regions 3′ and 5′ UTRs) suggesting GLRB as a candidate gene for agoraphobia." (PMID 32848605, 2020).
breast carcinoma (2 papers, 2019 to 2022). "Among other highly connected genes belonging to “visual perception”, GLRB (Glycine Receptor Beta) is among the ion channel genes that is associated with the clinical outcome in breast cancer." (PMID 31117943, 2019).
developmental delay (1 paper, 2019). "Moreover, patients with variants in GLRB and SLC6A5 are more likely to have a developmental delay than those with GLRA1 variants." (PMID 31604777, 2019).
glioma (1 paper, 2023). A benign or malignant brain and spinal cord tumor that arises from glial cells (astrocytes, oligodendrocytes, ependymal cells). "The most notable lncRNA is LINC00599, which has DBSs in many NGS genes in most gliomas, including GABBR1, NRCAM, PTPRS, GLRB, GRIA4, GRIK3, and MAP2, and the most notable NGS gene is MAP2, which is associated with microtube assembly and regulated by multiple lncRNAs through the same DBS." (PMID 37693314, 2023).
tumor (1 paper, 2022). "Thus, changes in the functioning of GLRB may promote tumor growth." (PMID 35326596, 2022).
GLRB also shares sentences with these, for which no sentence is quoted: anxiety disorder (2 papers); myopia (1).